NECTIN4 (nectin cell adhesion molecule 4)
Description:
Seems to be involved in cell adhesion through trans-homophilic and -heterophilic interactions, the latter including specifically interactions with NECTIN1. Does not act as receptor for alpha-herpesvirus entry into cells. (Microbial infection) Acts as a receptor for measles virus.
Synonyms: LNIR; PRR4; PVRL4; nectin-4; EDSS1
Tractability: Antibody: UniProt places it where antibodies can reach, with high confidence; its Gene Ontology location is reachable by antibodies, with high confidence; UniProt predicts a signal peptide or a membrane-spanning region; the Human Protein Atlas places it where antibodies can reach. Other modalities: an approved drug acts on it.
Target class: Adhesion
Safety:
Unwanted effects reported when the protein is acted on. In parentheses: how it was acted on, where the effect was seen, and who reports it.
skin irritation (source: ClinPGx)
Gene: Protein-coding gene on chromosome 1 (161,070,988 to 161,090,045, reverse strand). Ensembl gene ENSG00000143217.
Subcellular location: Cell membrane; Cell junction, adherens junction; Secreted (Processed poliovirus receptor-related protein 4)
Subcellular location (Human Protein Atlas): Plasma membrane; Predicted to be secreted
Pathways (Reactome):
Cell-Cell communication: Adherens junctions interactions; Nectin/Necl trans heterodimerization
Gene Ontology:
Molecular function: identical protein binding; protein binding; receptor ligand activity; cell adhesion mediator activity
Biological process: negative regulation of natural killer cell mediated cytotoxicity; heterophilic cell-cell adhesion; homophilic cell-cell adhesion; cell adhesion; signal transduction; symbiont entry into host cell
Cellular component: adherens junction; extracellular exosome; extracellular region; plasma membrane
Genetic constraint (gnomAD): Loss-of-function variants: 19 observed, 51.8 expected, observed/expected ratio (o/e) 0.37, 90% interval 0.25 to 0.54. The upper end of that interval is the gene's LOEUF score, 0.54, which puts it in group 2 of 6, group 1 being the genes least tolerant of losing a copy. Missense variants: 619 observed, 679.38 expected, observed/expected ratio (o/e) 0.91, 90% interval 0.85 to 0.97. Synonymous variants: 283 observed, 296.44 expected, observed/expected ratio (o/e) 0.95, 90% interval 0.87 to 1.05.
Homologues: Orthologues: chimpanzee NECTIN4 (100% identical), dog NECTIN4 (94% identical), rabbit NECTIN4 (94% identical), guinea pig NECTIN4 (92% identical), mouse Nectin4 (92% identical), rat Nectin4 (92% identical), pig NECTIN4 (90% identical), macaque NECTIN4 (79% identical), tropical clawed frog NECTIN4 (52% identical), zebrafish nectin4a (31% identical), zebrafish nectin4b (29% identical), Drosophila melanogaster Fas3 (17% identical). Paralogues in human: NECTIN3 (26% identical), NECTIN1 (23% identical), NECTIN2 (20% identical), PVR (19% identical), CADM3 (18% identical), CADM4 (17% identical), CADM1 (17% identical), CADM2 (17% identical), CD226 (13% identical), CRTAM (12% identical), CD200 (10% identical), TIGIT (9% identical), and 2 more.
Diseases named in the same sentence as NECTIN4 in open-access papers:
NECTIN4 is named in the same sentence as 132 diseases in open-access papers, as found by Europe PMC text mining. Sharing a sentence is not in itself a finding about the gene and the disease. The quoted sentences say what the papers report.
breast carcinoma (62 papers, 2007 to 2025). "In recent years, overexpression of Nectin-4 has been implicated in tumor occurrence and development of various cancers, including breast cancer, urothelial cancer, and lung cancer." (PMID 38606099, 2024). "Numerous studies have suggested a possible association between Nectin-4 expression and the prognosis of patients with various cancers, particularly breast cancer." (PMID 38606099, 2024). "In BLCA, BRCA, and LUAD—where EV is approved or in late-stage clinical development—NECTIN4 amplifications associated with increased NECTIN4 mRNA expression (Appendix Figs A4A and A4C) and higher NECTIN4 protein levels in breast cancer (Appendix Fig A4B)." (PMID 38657187, 2024). "Nectin-4 is a novel biomarker overexpressed in various types of cancer, including breast cancer, in which it has been associated with poor prognosis." (PMID 38288120, 2023). "Nectin-4 is a diagnostic and therapeutic target for lung cancer and breast carcinoma, and the epithelial cell receptor of measles virus." (PMID 32421739, 2020). "Unlike other Nectins, Nectin-4 is not expressed in normal adult tissue; however, several studies have found re-expression of Nectin-4 as a tumor-associated antigen in various cancer tissues, including pancreatic, ovarian, lung and breast cancer." (PMID 31572728, 2019). "In lung cancer, breast cancer, and pancreatic cancer, expression of Nectin-4 or detection of Nectin-4 in serum was associated with tumors progression or poor survival." (PMID 28038455, 2017). "We found Nectin-3 and Nectin-4 to be reduced in breast cancer and associated with good prognosis and patient outcome." (PMID 24386110, 2013). "We present here Nectin-4/PVRL4 as a new histological and serological tumor associated marker for breast carcinoma." (PMID 17474988, 2007). "In this study, we investigated the potential role of Nectin-4 as a new histological and serological tumor associated marker for breast carcinomas." (PMID 17474988, 2007). "We found that Nectin-4 expression is associated with markers that define the basal-like subtype of breast cancer." (PMID 17474988, 2007). "In the present study, we show that Nectin-4 is a new tumor-associated antigen and a reliable marker for breast carcinoma." (PMID 17474988, 2007). "However, in breast cancer, Nectin-4 expression has been associated with better survival rates, likely due to its effectiveness as a therapeutic target." (PMID 40699695, 2025). "Moreover, a large number of studies demonstrated that overexpression of Nectin-4 served as a tumor-associated inducer in various malignant tumors, including colorectal, lung, pancreatic, ovarian, and breast cancers." (PMID 35953862, 2022). "The authors concluded that Nectin-4 was a new tumour-associated antigen for breast carcinoma and a new bio-marker whose use could help refine breast cancer taxonomy and improve patient follow-up." (PMID 24386110, 2013). "Nectin-4 is a new tumor-associated antigen for breast carcinoma." (PMID 17474988, 2007). "It is also worth considering initiating studies to determine therapeutic possibilities arising from nectin-4 in breast cancer patients." (PMID 40244005, 2025). "Nevertheless, the collected data seem sufficient to conclude that further research on nectin-4 expression in breast cancers should focus on taking advantage of its identified diagnostic and prognostic potential." (PMID 40244005, 2025). "There is also an FDA-approved Nectin4 antibody–drug conjugate that is currently being used in bladder and breast cancer." (PMID 40717170, 2025). "Herein, we showed that lactate treatment in ER + ve breast cancer cells reduced nectin-4 expression and LDHB KO in ER- cells enhanced its expression." (PMID 40507273, 2025). "The adhesion molecule nectin-4 was shown to play a role in breast cancer pathogenesis, and its over-expression has been observed in various forms of cancers including breast, lung, colorectal, pancreatic, and ovarian cancers." (PMID 40507273, 2025).
breast carcinoma (continued). "Dysregulation of nectin-4 levels is observed in squamous cell carcinoma of the head and neck, kidney cancer, breast cancer, ovarian cancer, bladder cancer, pancreatic cancer, gastric cancer, and cancer of other parts of the digestive tract." (PMID 40244005, 2025). "This approach is supported by experiments in a breast cancer xenograft model showing that intratumoral injections of an antibody to Nectin-4 can stall tumor growth in vivo by disrupting cell–cell contacts." (PMID 40075748, 2025). "The transfection of the mouse breast cancer cell line 4T1 with human nectin-4 was confirmed using flow cytometry." (PMID 39978811, 2025). "Overexpression of TACE in breast cancer indicates that the formation of soluble Nectin-4, both in vitro and in vivo, can be attributed to TACE." (PMID 38606099, 2024). "Due to its mechanism of targeting nectin-4, EV is also being investigated for the treatment of other nectin-4-expressing malignancies, including gastrointestinal tumors, small cell lung cancer, and breast cancer." (PMID 39712492, 2024). "In breast cancer, Nectin-4 and tyrosine kinase receptor ErbB2 (also known as Her2) are highly expressed and can cis-interact with each other to activate the PI3K/AKT signaling pathway for DNA synthesis." (PMID 38606099, 2024). "Survivin is expressed in various tumor cells, and in breast cancer cells, it is correlated with the expression of Nectin-4." (PMID 38606099, 2024). "The authors synthesized a radionuclide probe 99mTc-HYNIC-mAbNectin-4 to assess nectin-4 expression in breast cancer xenografts in mice via immunoSPECT/CT imaging." (PMID 37568798, 2023). "The upregulation of nectin-4 was first reported in breast cancer, especially in ductal carcinomas, and positively correlated with basal-like markers, which often implies poor prognosis." (PMID 38288120, 2023). "The present study aims to produce nectin-4-specific single-chain variable fragment (scFv) antibodies and evaluate their applications in breast cancer cell lines and clinical specimens." (PMID 38288120, 2023). "Further, EV led to a significant reduction of tumor volume in Nectin-4 positive bladder cancer, breast cancer, and lung cancer xenografts and to a significant inhibition of tumor growth in Nectin-4 positive pancreatic cancer xenografts compared to controls." (PMID 37480387, 2023). "Selected clones L4 and S21 recognized the recombinant ectodomain of nectin-4 and successfully detected the endogenous nectin-4 in several breast cancer cell lines." (PMID 38288120, 2023). "The binding capacities of the selected clones were evaluated with the recombinant nectin-4 fragments, breast cancer cell lines, and paraffin-embedded tissue sections using various laboratory approaches." (PMID 38288120, 2023). "Abnormal expression of both membranous and soluble forms of Nectin-4 has been found in human breast cancer tissues and sera, and the levels of both forms of Nectin-4 can be used as important biomarkers and prognostic predictors in patients with breast cancer." (PMID 37345201, 2023). "Researchers exploited high nectin-4 expression rates in breast cancer and attempted to develop an oncolytic measles virus selectively blind to the signaling lymphocyte activation molecule (SLAMblind)." (PMID 37568798, 2023). "EV has shown dose-dependent inhibition of cell viability in human, rat, and monkey cell lines transfected to express Nectin-4 as well as breast cancer cell lines endogenously expressing Nectin-4." (PMID 37480387, 2023). "The virus, rMV-SLAMblind, targets nectin-4, recently listed as a tumor marker, and exerts antitumor activity against nectin-4-positive canine mammary cancer and urinary bladder transitional cell carcinoma cells." (PMID 37875555, 2023). "We demonstrated that rMV-SLAMblind can infect canine mammary cancer cells and urinary bladder transitional cell carcinoma expressing nectin-4 and exerts antitumor effect in vivo." (PMID 37875555, 2023).
breast carcinoma (continued). "A poorer prognosis of patients with Nectin-4 positive tumors has been reported for bladder cancer and esophageal cancer, whereas the data for breast cancer appears to be inconclusive so far." (PMID 36268557, 2022). "They observed the highest expression levels overall of nectin-4 in bladder (60%) and breast cancer (53%), in ovarian, head and neck and esophageal tumors the staining intensity was significantly lower." (PMID 36268557, 2022). "In breast cancer some studies link Nectin-4 expression with lower tumor stage and less lymph node involvement." (PMID 36268557, 2022). "It has also been reported that an interaction between breast cancer cell-derived NECTIN4 ecto-domain and integrin β4 promotes angiogenesis in HUVEC via Src signaling." (PMID 35256687, 2022). "For example, if nectin-4 is expressed on the surface of metastatic breast cancer cells, its extracellular domain falls off and is released into the microenvironment." (PMID 34439865, 2021). "NECTIN4 also supports the tumor progression of breast cancer cells by promoting anchorage-independent growth and cell proliferation through cell–cell interactions." (PMID 33808400, 2021). "Integrin β4 physically interacts with the ecto domain of nectin-4, and then promotes angiogenesis in metastatic breast cancer stem cells (mBCSCs) via the Src, PI3K, AKT, and iNOS pathways." (PMID 34439865, 2021). "The reason why human breast cancer T47D cells were used was that they endogenously express both nectin-4 and ErbB233." (PMID 33795719, 2021). "Nectin-4 expression by IHC on >760 breast carcinoma samples revealed that nectin-4 was more prominently expressed in ductal breast cancer where strong cytoplasmic expression was observed." (PMID 34358100, 2021). "Under hypoxia, the expression of ADAM-17 driven by metastatic breast cancer stem cells (mBCSCs) leads to the shedding of the extracellular domain of nectin-4 into the microenvironment and interacts with integrin β4 in the microenvironment." (PMID 34439865, 2021). "In recent years, nectin cell adhesion molecule 4 (NECTIN4) has been identified as an important factor in several malignant tumors, including urothelial carcinoma, gastric cancer, thyroid cancer, breast cancer, esophageal cancer, and ovarian cancer." (PMID 32824340, 2020). "In breast cancer cells, where Nectin-4 promotes anchorage-independent growth, antibodies against Nectin-4 have been shown to block the growth of tumor cell implants in mice." (PMID 32629816, 2020). "To clarify the possibility that MV vector targeting Nectin-4 is applicable for the tree shrew mammary tumor model, we stained mammary tumor cells with anti-Nectin-4 antibody." (PMID 32421739, 2020). "Further, growth of orthotopically implanted breast cancer cells in nude mice can be inhibited by blocking PVRL4 (NECTIN4)-driven cell-to-cell attachment with monoclonal antibodies against PVRL4." (PMID 31137558, 2019). "The abnormal expressions of both membranous and soluble forms of Nectin-4 have been found in human breast cancer tissues and sera from the patients." (PMID 31043861, 2019). "Two other studies investigated Nectin-4 expression by immunohistochemistry in luminal-A breast cancers and in a mixed cancer cohort." (PMID 31572728, 2019). "In their study high Nectin-4 expression in a breast cancer cohort of mixed molecular subtypes and also specifically in TNBC was associated with a lower metastasis free survival." (PMID 31572728, 2019). "In both, localized and metastatic triple negative and Nectin 4-positive breast cancer this therapy led to rapid and long-lasting regression in mice xenograft models." (PMID 31137558, 2019). "We further analyze two independent breast cancer datasets and find that specific isoforms of IGF2BP2, NECTIN4, ITGB6, and KLHDC9 are significantly associated with AZD6244, lapatinib, erlotinib, and paclitaxel, respectively." (PMID 29066719, 2017).
breast carcinoma (continued). "In breast cancer cells, Nectin-4 expression promotes anchorage independent cell survival and proliferation through cell-cell adhesion." (PMID 28038455, 2017). "In other study, Nectin-4 promotes the attachment of individual cells to each other on a juxtaposed cell, and maintains the transformed properties of breast cancer cells in vitro." (PMID 25888293, 2015). "A few previous reports have shown that Nectin-4 expression contributes to the postoperative prognosis of patients with malignant tumors including lung adenocarcinoma and breast cancer." (PMID 25888293, 2015). "It was recently reported that Nectin-4 is overexpressed in several human cancers, including lung, ovarian, and breast cancer." (PMID 25888293, 2015). "We thus looked for the presence of a Nectin-4 circulating form in the sera of patients with breast carcinoma." (PMID 17474988, 2007). "Nectin-4, non expressed in normal cells, is prominently expressed in breast carcinoma cell lines and in breast tumor samples." (PMID 17474988, 2007). "Nectin-4 and serum Nectin-4 should serve as a new taxonomic, prognosis, and follow-up marker for breast cancer." (PMID 17474988, 2007). "They found that higher levels of m-nectin-4 expression are significantly associated with a lower disease-free survival (DFS) rate and a lower distant recurrence-free survival (DRFS) rate in patients with luminal-A breast cancer." (PMID 40244005, 2025). "In the context of breast cancers, the expression of nectin-4 appears to be sufficiently well understood that, in addition to the potential utilization of the data for prognostic and diagnostic purposes, there is a strong likelihood of the emergence of attempts at therapeutic use in the near future." (PMID 40244005, 2025). "Nectin‐4 (PVRL4) is expressed in cancer tissues such as breast cancer." (PMID 38738791, 2024). "Two selected scFv clones could capture the ectodomain of nectin-4 and recognize endogenous nectin-4 on several breast cancer cell lines, with scFv L4 demonstrating better sensitivity and specificity to identify nectin-4 in its native form." (PMID 38288120, 2023). "Overall, the nectin-4-specific scFvs could recognize nectin-4 expressed by breast cancer cells and have the merit of being further explored for potential diagnostic and therapeutic applications." (PMID 38288120, 2023). "L4 could also stain the other nectin-4-positive breast cancer cell lines (including BT-474 and MDA-MB-453) and Vero-hNectin-4 cells." (PMID 38288120, 2023). "There is a wide range of studies concerning the role of nectin-4 in breast cancer." (PMID 37568798, 2023). "Nectin-4-positive breast cancer cells easily formed cell clusters in suspension." (PMID 38288120, 2023). "In a breast cancer, Nectin-4 was predominantly overexpressed in ductal breast carcinoma tissues." (PMID 37174031, 2023). "In addition, nectin-4 is also considered a breast cancer stem cell marker, as its presence enhances cell invasion and epithelial-mesenchymal transition and activates the Wnt/β-catenin pathway through the PI3K/Akt axis." (PMID 38288120, 2023). "Given that nectin-4 plays a vital role in the carcinogenesis of breast cancer, we further explored whether the scFvs could inhibit cell growth in vitro." (PMID 38288120, 2023). "Recent investigations revealed that Nectin-4 is involved in several facets of tumor progression, including proliferation, angiogenesis, and epithelial-to-mesenchymal transition in various cancers, including breast cancer." (PMID 35614462, 2022). "Nectin-4, upregulated in various cancer cells, cis-interacts with ErbB2 and its trastuzumab-resistant splice variants, p95-ErbB2 and ErbB2∆Ex16, enhancing DNA synthesis through the PI3K-AKT signaling in human breast cancer T47D cells in an adherent culture." (PMID 33795719, 2021). "In addition to these markers, Nectin-4 has been also reported to be expressed in breast cancer cells and Nectin-4 targeted oncolytic measles virus (MV) vector has been constructed." (PMID 32421739, 2020).